SNAI2 (snail family transcriptional repressor 2)
Diseases named in the same sentence as SNAI2 in open-access papers (continued):
Sharing a sentence is not in itself a finding about the gene and the disease.
tumor (continued). "In addition, SNAI2 expression was highly expressed in most tumor cells according to the CCLE database." (PMID 37251370, 2023). "SNAI2 was associated positively with the degree of infiltration of CAF, Endo, Gran, HSC, Neutrophil, monocyte, and macrophage in most cancers, which suggested SNAI2 was most likely to affect the development and prognosis of cancers by shaping the tumor microenvironment." (PMID 37251370, 2023). "Studies have reported that FOSL2 can interact with Smad3, Wnt5a, or SNAI2 to promote tumour growth." (PMID 37380804, 2023). "In addition, Snai2 is activated by HIF1α under hypoxia in the tumor microenvironment to promote metastasis." (PMID 37377752, 2023). "Similarly, It was also found that oxymatrine in combination with 5-Fu treatment efficiently regulated tumor cells EMT through effective modulation of the expressions of Snai2, vimentin, E-cadherin, and p-NF-κB p65 in HCT-8/5-Fu cells." (PMID 35308223, 2022). "Therefore, SNAI2 expression is correlated with the immunosuppressive tumor immune microenvironment in different manners in primary and metastatic PC, which supports the distinct clinical relevance of SNAI2 expression at different stages of the disease." (PMID 34792282, 2022). "Interestingly, an addition of tumor cells results in a decreased expression of SNAI2 (Co1/1, p = 0.0045)." (PMID 36552039, 2022). "Silencing of SNAI2 facilitated tumor cell proliferation and luminal differentiation." (PMID 34792282, 2022). "Additionally, tumor-associated macrophage (TAM), the metastasis stimulator, is capable of secreting TGFβ to impair EpCAM expression probably through SNAI2." (PMID 36077658, 2022). "Furthermore, the p-mTORC and p-Akt expression increased upon oe-SNAI2 but decreased following oe-PHLPP2 when compared to oe-NC in nude mice xenografted with tumor." (PMID 35654777, 2022). "Since EMT has been shown to be an important factor in tumor progression, its facilitator SNAI2 may have an even more important role in RCC carcinogenesis." (PMID 36338978, 2022). "Our data suggested that CHD1L might be targeted to revert the induced SNAI2 expression thus re-sensitize tumor cells that have acquired resistance to Talazoparib." (PMID 35864202, 2022). "We revealed that T2E is involved in the silencing of SNAI2 and may be essential for aberrant tumor cell proliferation and luminal differentiation." (PMID 34792282, 2022). "For example, a defect in tumor development such as that seen with SNAI2 (Snail family transcriptional repressor 2) also translates into a defect in lesion repair, and Snai2-deficient CAFs have a lower capacity for producing some important cytokines in these processes." (PMID 36292921, 2022). "The expression of CSRP1, MYL9 and SNAI2 changed in different tumor stage." (PMID 35768705, 2022). "Conversely, treatment with a TGFβ signaling inhibitor reduced ZEB1 and SNAI2 levels and prevented the acquisition of mesenchymal marker expression and morphological features, thus linking mesenchymal differentiation in Rb with enhanced tumor cell invasion through the TGFβ/ZEB1/SNAI2 axis." (PMID 36291907, 2022). "Moreover, oe-SNAI2 + oe-PHLPP2 resulted in alleviated tissue injury when compared to oe-PHLPP2 in nude mice xenografted with tumor." (PMID 35654777, 2022). "Interestingly, DEAR1/TRIM62 has been reported to suppress tumor metastasis through inhibiting MAPK/JNK-induced SNAI2 expression." (PMID 36376460, 2022). "The association between SNAI2 and the S2 (P1) or S3 (P2/P3) region of the MTO1 promoter was verified using the ChIP assay and further confirmed by a luciferase reporter gene assay in human granulosa-like tumor cells." (PMID 34413875, 2021). "We found a novel SNAI2/circMTO1/miR-320b/MCL1 axis in human granulosa-like tumor cell progression." (PMID 34413875, 2021). "Therefore, our results revealed that the expression of circMTO1 in human granulosa-like tumor cells was facilitated by SNAI2." (PMID 34413875, 2021).
tumor (continued). "Additionally, we show that combining SNAI2 reduction with standard of care vincristine results in synergistic reduction in tumor volume and robust enhancement of muscle differentiation." (PMID 33420019, 2021). "SNAI2 positively regulated circMTO1 expression in human granulosa-like tumor cells." (PMID 34413875, 2021). "Additionally, circMTO1 expression in human granulosa-like tumor cells was positively regulated by SNAI2." (PMID 34413875, 2021). "Snai2 was found to associate with the gender, histological variants, BRAF/RAS phenotype, and lymph node metastases, while Zeb1 was found to be associated significantly with the histological variants, BRAF phenotype, tumor size, and disease recurrences." (PMID 34575184, 2021). "Furthermore, we found that the expression of circMTO1 was induced by Snail family transcriptional repressor 2 (SNAI2) in human granulosa-like tumor cells." (PMID 34413875, 2021). "Meanwhile, SNAI2 also induced the expression level of circMTO1 in human granulosa-like tumor cells." (PMID 34413875, 2021). "Furthermore, we confirmed SNAI2 as an upstream transcription factor of circMTO1 in human granulosa-like tumor cells." (PMID 34413875, 2021). "Blocking of ligand activation of Notch (all receptors) by using a soluble Notch4 exodomain (XNotch4) in BrCa xenografts promoted apoptosis and reduced tumor size and metastasis concomitantly to SNAI2 expression reduction, CDH1 upregulation, and active β-catenin suppression." (PMID 33430387, 2021). "Moreover, several previous studies demonstrated that expression of CDH2 has a positive correlation with SNAI2 in tumor tissues." (PMID 32788880, 2020). "Furthermore, the researchers pointed out the connection between this relationship and the resistance of neoplasm cells to anticancer therapy, which is consistent with other papers describing SNAI2." (PMID 32349263, 2020). "Meanwhile, in vivo studies showed that SNAI2 could promote the tumor progression, and HOTAIRM1 knockdown reversed this results." (PMID 33323548, 2020). "However, in the tumor section where KLF4 loss was observed, we noticed increased levels of SNAI2 in the nuclei of the epithelial cells that were defined by positive staining for PanCK." (PMID 32566755, 2019). "Furthermore, CAR10 knockout successfully decreased the expression of SNAI1 and SNAI2 and inhibited tumor proliferation and metastasis in vivo." (PMID 30617305, 2019). "Furthermore, the decreased methylation of the SNAI2 gene in tumours with histologic grade 3 indicates a new function of a typical EMT gene in cancer cell de-differentiation." (PMID 30189837, 2018). "The influence of the methylation of EMT-associated genes (TWIST1, SNAI1 and SNAI2) and the clinico-histopathological features of invasive BC, namely, age, HR and HER2 status, tumour histology and Ki-67 proliferative index on tumour grade were assessed in a multivariate model." (PMID 30189837, 2018). "Meanwhile, the distinct expression pattern of SNAI1 and SNAI2 in cancer cells and fibroblasts coincides with the context-dependent role of TFs, for which the expression shift implied a unique role for SNAI1 and SNAI2 in the tumor and stromal compartment, respectively." (PMID 29041931, 2017). "Moreover, as a classic TF regulating the EMT program in various tumor cells, SNAI2 was supposed to control the cascade of downstream effector gene activation." (PMID 29041931, 2017). "In accordance, we discovered that SNAI2 expression was correlated with the stromal component and was most highly expressed in the mesenchymal cluster, implying that SNAI2 expression was enriched in subtypes with reactive tumor stroma." (PMID 29041931, 2017). "Our observations suggest that the inhibition of SNAI2 and the regulated mesenchymal signature to target stromal activation could be a potential approach in targeting the cooperative tumor stroma of OC." (PMID 29041931, 2017).
tumor (continued). "Moreover, SNAI2 and its defined signature were strongly correlated with tumor stroma activation and OC patient survival." (PMID 29041931, 2017). "In addition, miR-203 inhibits proliferation, migration, EMT and tumor angiogenesis in a variety of tumor cells by targeting SNAI2, which in turn suppresses miR-203, forming a double negative feedback loop for the regulation of EMT." (PMID 29064439, 2017). "Thus, we demonstrated here that SNAI2 reprogram normal quiescent fibroblasts into a proinvasive phenotype that fuels tumor cell growth and invasion." (PMID 29041931, 2017). "In addition, the reduced expression of SNAI2 in epithelial cells along tumor progression was further confirmed in ovarian and breast profiles." (PMID 29041931, 2017). "A majority of studies on SNAI2 have focused on its role in tumor cells." (PMID 29041931, 2017). "SNAI2 was very weak and only found in a small number of tumour cells (2/60)." (PMID 29115924, 2017). "At the end of the experiment, tumor tissues were subjected to Masson’s trichrome staining and immunological evaluation of aSMA, showing that the matrix content in tumors of the Ade-SNAI2 co-injection group was the strongest, followed by the Ade-nc co-injection group and the SKOV3-Luc solitary group." (PMID 29041931, 2017). "Our data showed that SNAI2 knockdown could reinforce anchorage-independent growth of HCC cells in tumor sphere culture and soft agar clone formation assay." (PMID 27760172, 2016). "The SNAI2/Slug gene is a major regulator of cell migration and tumor metastasization." (PMID 25686823, 2015). "Interestingly, Slug (Snai2) another gene that governs tumor invasiveness, whose expression was also regulated by TMEPAI just like Snai1in cancer cells (data not shown)." (PMID 25352949, 2014). "In addition to FN1 and SPARC, other well-established EMT-associated genes are also upregulated in these tumor samples following letrozole treatment including TWIST1, SNAI2, ZEB1, and ZEB2." (PMID 24944582, 2014). "Whether LEF1 or SNAI2 could recover IGF2BP1 knockdown-induced impairment of tumor cell migration was determined by their stable expression in IGF2BP1-depleted cells." (PMID 23677615, 2013). "They identified SNAI2, a member of the Snail family of zinc finger transcription factors - because it has been implicated in epithelial-mesenchymal transition (EMT) and tumor metastasis, as a direct functional target of miR-124." (PMID 23936026, 2013). "Importantly, following EGF treatment, we detected elevated transcript levels of several MUC1 target genes linked to tumor cell invasion including TWIST, SNAI1, and SNAI2." (PMID 22586492, 2012). "Staining of tumor vasculature using a CD31 antibody revealed increased vascular proliferation in tumors in which SNAI2/Slug was overexpressed when compared to control tumors (19 +/- 4 CD31 positive vessels/hpf versus 8 +/- 1 CD31 positive vessels/hpf, P < 0.002, t-test)." (PMID 20565806, 2010). "SNAI2, Zeb2 and other family members have multiple gene targets and can recruit specific chromatin-remodelling complexes that repress E-cadherin (CDH1), which is frequently downregulated in tumor progression and EMT and implicated in lymph node metastasis." (PMID 18638373, 2008). "Furthermore, in gastric cancer, SNAI2 also plays an important role in tumor progression." (PMID 37251370, 2023). "While we found the higher expression of MMP3 in TC vs. AC, despite the lower aggressiveness of the former tumor type, the higher expression of SNAI2 may justify some TC cases with favorable pathologic features following an unpredictable unfavorable clinical course." (PMID 36553576, 2022). "Additionally, SNAI2 in the tumor microenvironment can facilitate EMT accompanied by tumorigenesis." (PMID 34440070, 2021).
tumor (continued). "Moreover, SNAI2 knockdown cells are poised towards differentiation, and in this context, treatment with vincristine can synergistically enhance differentiation and exit of tumor cells from the cell cycle resulting in significant reduction in tumor growth." (PMID 33420019, 2021). "Besides, biomarker of EMT such as SNAI2 in the tumor microenvironment could also facilitate EMT process accompanied with tumorigenesis." (PMID 34440070, 2021). "Based on the assumption that decreased methylation could allow the up-regulation of SNAI2 gene expression, reduced differentiation in tumours could be expected, as was observed in our study by the inverse relationship between SNAI2 methylation and histologic grade." (PMID 30189837, 2018). "Finally, we constructed a 3-dimentional (3D) organotypic coculture model that faithfully represented the histological and biological microenvironment of OC metastasis, to evaluate the effect of SNAI2 upregulation on the ability of CAFs to affect tumor cell growth." (PMID 29041931, 2017). "However, SNAI2 could behave as a tumor suppressor through inhibiting proliferation, driving cell differentiation, and repressing tumor-initiation." (PMID 27760172, 2016). "In contrast, in a recent report depicting six master regulators (AEBP1, HOPX, PRRX1, SNAI2, ZEB1, ZEB2) of the TCGA “mesenchymal” subtype, they employed a network-based strategy to uncover the molecular mechanism underlying the discrete mesenchymal subtype in whole tumor tissues of serous OC." (PMID 27081703, 2016). "Thus, the regulation of these genes by Snai2 in response to DNA damage could be important in preserving integrity of tumour target cells and supports the view that failure to control Snai2 expression can produce cancer and alterations in development." (PMID 18182996, 2008). "Thus, constitutive activation of Snai2 could confer resistance properties to the tumour-target cells connecting DNA damage with the requirement of a critical level of Snai2 for cancer development." (PMID 18182996, 2008). "The identification of gene co-expression modules containing classical EMT markers (e.g., VIM, ZEB1, SNAI2) alongside ECM-related genes (COL1A1, FN1, SPARC, LOX) underscores a tightly coordinated interaction driving tumor cell plasticity and invasion." (PMID 40943497, 2025). "While some studies have investigated the role of TCM in inhibiting tumor spread by reducing SNAI2 expression, the mechanistic exploration of how DBD and its bioactive compounds modulate SNAI2 expression to inhibit BC progression remains underexplored." (PMID 41356226, 2025). "MMP2, COL6A3, PRRX1, COL1A2, GREM1 and SNAI2 are integral to the EMT process, a key driver of metastasis that allows tumor cells to detach and invade distant tissues." (PMID 39920655, 2025). "We also excluded five markers that showed expression in both tumor subtypes (AGR2, SNAI2, KRT6A, MET, SLC16A3)." (PMID 39935174, 2025). "In the colon-derived cells, during the transition from a healthy to a tumor cell and then to a metastatic cell type, we observed a gradual increase in the EMT-TF genes SNAI2 and ZEB1, and in VIM, CDH5 and MMP2." (PMID 40332096, 2025). "Several tumor-specific TFs were detected within the ED and SED, including TP63, FOSL1, JUND, GRHL2, SNAI2, KLF5, TP73, and SMAD3." (PMID 41323280, 2025). "We showed that the initiation of EMT by INHBA is mediated by the upregulation of SNAI2 and SNAI1, rendering tumor cells more migratory." (PMID 38329386, 2024). "To investigate the impact of SNAI2 on RMS metastasis in vivo, we established tumor xenografts in zebrafish embryos.The results indicated that compared to the shSNAI2 group, the NC group showed a significant rise in metastatic tumor cell count." (PMID 38702792, 2024). "A strong positive correlation was detected between the expression of INHBA and EMT transcription factors SNAI1 (Rho = 0.62), SNAI2 (Rho = 0.82), and TWIST1 (Rho = 0.69) in the primary tumor." (PMID 38329386, 2024).
tumor (continued). "This study analyzed the expression of SNAI2 in 34 primary RMS samples, 25 metastatic tumor samples, and 12 normal muscle tissue samples collected from Zhengzhou University Children's Hospital between 2010 and 2022." (PMID 38702792, 2024). "Snai2 was the most frequently and strongly expressed marker of EMT in both tumor types (10/10 UC, 8/16 UCOGC), and its expression was higher in UC than in UCOGC." (PMID 38790924, 2024). "Combined expression of WNT ligands (WNT3A, WNT4, WNT7B, WNT9A, WNT10A, WNT11) in BRCA patient tumours has a positive correlation (R = 0.27, p value = 0) with the combined expression of key EMT-inducing transcription factors SNAI1, SNAI2, ZEB1, ZEB2 and TWIST1." (PMID 38678032, 2024). "During EMT, tumor cells lose their epithelial phenotype (E-cadherin expression) and express mesenchymal markers, such as N-cadherin, SNAI1, SLUG (SNAI2), TWIST, vimentin, fibronectin." (PMID 39605887, 2024). "CircMTO1 was found to mediate the progression of human granulosa-like tumor cells through the miR-320b/MCL1 axis, promoted by increased transcription of SNAI2." (PMID 38255975, 2024). "The results presented here support previous work from our group using in vitro and murine models which found that SNAI2 expression was seen in low grade PanIN and induced FSCN1 expression in cells cultured from tumours." (PMID 37832352, 2023). "According to miRDB: the microRNA database, miR-181a-5p has 887 target genes, including BCL2, LMO3, PTEN, SNAI2, WIF1, which are related to tumor development, cell cycle control, signal transduction processes, and apoptosis." (PMID 37697308, 2023). "Tumour cells in a hybrid E/M state possessed moderated expression levels of GRHL2, OVOL1, ZEB1 and SNAI2." (PMID 36808651, 2023). "Mechanistically, KLF5 exerts its tumor promotion effect by up-regulating fibroblast growth factor binding protein 1 (FGF-BP1) and snail family transcriptional repressor 2 (SNAIL2)." (PMID 38087142, 2023). "In total, the substantial relationship between SNAI2 and TMB, and MSI in tumor samples was demonstrated in this investigation." (PMID 37251370, 2023). "Conversely, tumour cells in the mesenchymal state possessed low expression levels of GRHL2 and OVOL1, high expression levels of ZEB1 and SNAI2." (PMID 36808651, 2023). "Interestingly, some of the common down-regulated genes, such as EPHA7 and NSUN7, are known for both their tumor suppressing and promoting roles, or are associated with overall survival (OS) (SLC22A31), while others have clear pro-tumorigenic roles (ADGRF1, LOX, LY6G5C, SNAI2, TNFRSF11B, ZNF233)." (PMID 36769365, 2023). "The tumour cells in the epithelial state possessed elevated expression levels of GRHL2 and OVOL1, low expression levels of ZEB1 and SNAI2." (PMID 36808651, 2023). "In HN257, CytoTRACE showed a distinct de-differentiated sub-population in the primary tumor that had high EMT scores and expression of SNAI2." (PMID 36973261, 2023). "MYC+MEL cells were increased in LN+AM and expressed high levels of MYC, MITF, SNAI2, and KIT, all of which play crucial roles in tumor progression." (PMID 38065972, 2023). "Consistent with the INPP4B tumor suppressor function, the tumorigenic markers MAPK, SRC, and SNAI2 were elevated, and the tumor suppressor proteins RB1, BRCA1, and CHEK2 were decreased in the cells treated with siRNA targeting INPP4B." (PMID 38001678, 2023). "Statistically significant differences were found only between SNAI2 expression and NSCLC patients’ tumor histology (p = 0.035) and lymph nodes status (p = 0.048)." (PMID 37697308, 2023). "Crucially, C3AR1 is positively correlated with 18 tumor metastasis related genes including FN1, SNAI2, and ZEB2." (PMID 37005667, 2023). "Snai2 promotes tumor cell metastasis through epithelial–mesenchymal transition (EMT), and Snai2 overexpression predicts poor prognosis in patients derived from various cancer types." (PMID 37377752, 2023).